CD109 (CD109 molecule)
Diseases named in the same sentence as CD109 in open-access papers (continued):
Sharing a sentence is not in itself a finding about the gene and the disease.
cancer (continued). "Our findings indicate that hBM-MSCs inhibit the malignant conversion of SSC cells by a paracrine effect via released factors and link the cancer inhibitory effect of hBM-MSCs to the TGF-β co-receptor, CD109." (PMID 29221155, 2017). "This represents the first report linking the cancer inhibitory effect of hBM-MSCs to CD109, and CD109-mediated suppression of TGF-β-induced EMT, migration, invasion and stemness in cancer cells." (PMID 29221155, 2017). "Therefore, in this study, for the first time, we investigated the relative expression and co-expression and prognostic significance of all members of the HER family with EGFRvIII, and cancer stem cell biomarkers CD44 and CD109 in patients with GBM." (PMID 40227788, 2025). "This study examined whether the expression of EGFRvIII is accompanied by the co-expression with other members of the HER family and putative cancer stem cell biomarkers CD44 and CD109." (PMID 40227788, 2025). "In triple-negative breast cancer (TNBC), CD109 expression is increased in cancer stem cells from TNBC patients as compared to non-TNBC samples, and is linked to chemotherapeutic resistance, increased distant metastasis, and poorer disease-specific survival." (PMID 39990858, 2024). "Although a pro-tumorigenic role for CD109 has been shown in non-SCC cancers, and in one type of SCC, the mechanisms and signaling pathways reported are discrepant." (PMID 35954339, 2022). "CD109, a member of the α2 macroglobulin (α2M)/C3 family, is a glycosyl-phosphatidylinositol (GPI)-anchor cell surface glycoprotein highly expressed in many cancers, including SCCs." (PMID 35954339, 2022). "CD109 was originally found on endothelial cells, platelets, and activated T-cell of human, it was shown to interfere with TGF-β signaling, to be highly expressed in some cancer diseases, and to play role in bone metabolism." (PMID 31936127, 2020). "Interestingly, CD109 and KIAA0125 (FAM30A) were previously identified by other groups to have prognostic relevance in cancer." (PMID 30050054, 2018). "Moreover, siRNA-mediated knockdown of CD109, a TGF-β co-receptor and potent inhibitor of TGF-β signaling, reveals a critical role of CD109 in mediating the anti-cancer effects of hBM-MSC-CM." (PMID 29221155, 2017). "Altogether, our results indicate that overexpression of CD109 in SCC cells led not only to a reduction in EMT marker expression, but also to a decrease in Sox2 expression and spheroid formation, indicating a reduction in the cancer stem cell population." (PMID 29221155, 2017). "However we believe that the data encourage a larger study on the predictive potential of CD109+ CEC in GBM and possibly other cancer patients treated with bevacizumab." (PMID 24069296, 2013). "Furthermore, CD109’s potential involvement in the IL-6/GP130/STAT3 axis, a key driver of chronic inflammation and cancer stem cell survival, suggests it may help sustain an inflammatory environment that fosters metastasis and immune evasion." (PMID 39990858, 2024). "Moreover, activation of YAP participated in CD109-mediated EMT and cancer stemness properties." (PMID 33375719, 2020). "However, treatment with these two antibodies did not affect the proliferation or migration in vitro of CD109 overexpressing cancer cell lines (data not shown), nor resulted in the down-regulation of CD109 antigen." (PMID 29731998, 2018). "However, increasing evidence suggests that CD109 may play a pro-metastatic role in several types of non-SCC cancers." (PMID 35954339, 2022). "CD109 has been reported as a TGF-β coreceptor with high affinity for the TGF-β subtype and inhibiting TGF-β signaling in vitro, thus has been studied as a therapeutic target for diseases in which TGF-β may play a pathophysiological role and a key to elucidate pathogenesis of certain cancers." (PMID 23509816, 2013).
blood cancers (1 paper, 2024). "The identification of CD109 as a biomarker in AML suggests its potential utility in other blood cancers, both as a diagnostic tool and a therapeutic target." (PMID 39990858, 2024). "CD109 has been studied predominantly in the context of solid tumors, but its role in hematological neoplasms is gaining attention." (PMID 39990858, 2024). "By influencing immune regulation and inflammation, CD109 could represent a key hub in the interaction between hematological neoplasms and their inflammatory microenvironments." (PMID 39990858, 2024).
cardiovascular disease (1 paper, 2024). "Several proteins linked to increased risk of cardiovascular disease were upregulated in male iVSMCS (PCK2, CD109, and IGFBP2)." (PMID 39796045, 2024).
infection (1 paper, 2024). The state of being infected such as from the introduction of a foreign agent such as serum, vaccine, antigenic substance or organism. "In particular, CD109 directly mediates the binding of KSHV virions to the cell surface during infection." (PMID 39666389, 2024). "To confirm the role of CD109 in mediating binding of KSHV virions to the cell surface during infection, we established stable CD109 and caveolin-1 cell lines in 293T cells." (PMID 39666389, 2024). "We further examined whether KSHV virions directly bind to CD109 and caveolin-1 during infection of senescent HuARLT cells." (PMID 39666389, 2024). "Throughout systematic examination involving the use of KO clones and cells overexpressing candidate proteins, we discovered that CD109 had an essential role in KSHV attachment and infection in human endothelial cells, particularly in senescent cells." (PMID 39666389, 2024). "Hence, KSHV virions directly bind to CD109 during entry into cells, and the enhanced expression of CD109 in senescent cells promotes KSHV entry and infection." (PMID 39666389, 2024). "Furthermore, when recombinant CD109 and KSHV virions were mixed and used for infection, we observed a decrease in KSHV infection rate proportional to the amount of recombinant CD109 added." (PMID 39666389, 2024).
metabolic disorders (1 paper, 2024). "Notably, several studies have revealed the role of CD109 in bone immune regulation and metabolic disorders, but there remains controversy." (PMID 38885217, 2024).
musculoskeletal diseases (1 paper, 2015). "CD109 has been detected in the peripheral circulation and SF as a component of CD146-positive lymphocytes in patients with numerous musculoskeletal diseases." (PMID 25819577, 2015).
CD109 also shares sentences with these, for which no sentence is quoted: adenocarcinoma (5 papers); esophageal squamous cell carcinoma (2); large cell carcinoma (2); oral cancer (2); penile squamous cell carcinoma (2); small cell carcinoma (2); adenosquamous carcinomas of the gallbladder (1); Alzheimer disease (1); autoimmune thyroid disease (1); bladder squamous cell carcinoma (1); bone marrow failure (1); cancer of the oral cavity (1); cardiomyopathy (1); choriocarcinoma (1); chronic rhinosinusitis (1); connective tissue disorder (1); cutaneous squamous cell carcinoma (1); embryonal carcinoma (1); embryonal tumors (1); endometrial adenocarcinoma (1); Ewing sarcoma (1); germ cell tumours (1); herpesvirus infection (1); inflammation (1); ischemic stroke (1); Kaposi's sarcoma (1); lung fibrosis (1); lung squamous cell carcinomas (1); medulloblastoma (1); metastatic cancer (1).
A further 13 diseases each share a sentence with CD109 in 1 paper.